EVX1 (even-skipped homeobox 1)
Description:
May play a role in the specification of neuronal cell types.
Synonyms: EVX-1
Tractability: No criterion of Open Targets' tractability assessment is met for any kind of drug.
Gene: Protein-coding gene on chromosome 7 (27,242,700 to 27,250,493, forward strand). Ensembl gene ENSG00000106038.
Subcellular location: Nucleus
Subcellular location (Human Protein Atlas): Nucleoplasm
Gene Ontology:
Molecular function: sequence-specific double-stranded DNA binding; DNA-binding transcription factor activity; DNA-binding transcription factor activity, RNA polymerase II-specific; RNA polymerase II cis-regulatory region sequence-specific DNA binding; DNA binding
Biological process: regulation of transcription by RNA polymerase II; regulation of DNA-templated transcription
Cellular component: chromatin; nucleus; axon; cell body
Genetic constraint (gnomAD): Loss-of-function variants: 19 observed, 25.41 expected, observed/expected ratio (o/e) 0.75, 90% interval 0.52 to 1.1. The synonymous counts are far from expectation, so gnomAD's model fits this gene poorly and the ratio says little. Missense variants: 660 observed, 550.97 expected, observed/expected ratio (o/e) 1.2, 90% interval 1.12 to 1.28. Synonymous variants: 324 observed, 261.23 expected, observed/expected ratio (o/e) 1.24, 90% interval 1.13 to 1.36.
Homologues: Orthologues: macaque EVX1 (99% identical), chimpanzee EVX1 (99% identical), mouse Evx1 (94% identical), pig EVX1 (94% identical), rat Evx1 (94% identical), rabbit EVX1 (93% identical), dog EVX1 (93% identical), guinea pig EVX1 (80% identical), tropical clawed frog evx1 (69% identical), zebrafish EVX1 (55% identical). Paralogues in human: EVX2 (53% identical), ARX (20% identical), PITX1 (17% identical), PITX3 (16% identical), PAX7 (16% identical), PITX2 (16% identical), PAX3 (16% identical), RAX (16% identical), UNCX (16% identical), VSX2 (16% identical), OTX1 (15% identical), ALX4 (15% identical), and 38 more.
Diseases named in the same sentence as EVX1 in open-access papers:
EVX1 is named in the same sentence as 18 diseases in open-access papers, as found by Europe PMC text mining. Sharing a sentence is not in itself a finding about the gene and the disease. The quoted sentences say what the papers report.
lung carcinoma (3 papers, 2013 to 2014). "Our results suggest that MEOX2, HDAC9, TWIST1, AhR and EVX1 overexpression from the 7p21 locus may be novel lung cancer or NSCLC tumor markers." (PMID 25460568, 2014). "EVX1 and OTX2 were identified as methylated in NSCLC and lung cancer." (PMID 24369052, 2013).
breast carcinoma (1 paper, 2019). "Four of the ten closest genes with probes available showed moderate association with breast cancer survival at P < 0.005 (HOXA9, HOTTIP, EVX1 and TAX1BP1), with these associations mainly observed for ER-negative breast cancer." (PMID 30787463, 2019).
Cirrhosis (1 paper, 2014). A chronic disorder of the liver in which liver tissue becomes scarred and is partially replaced by regenerative nodules and fibrotic tissue resulting in loss of liver function. "A more focused analysis of one gene within the HOXA locus, EVX1, demonstrates that DNA hypermethylation encompassing a block of ~5,000bp is observed in cirrhosis (relative to normal), increases in HCC, and increases further still in HCC cell lines." (PMID 25294808, 2014).
esophageal squamous cell carcinoma (1 paper, 2023). Esophageal squamous cell carcinoma (ESCC) is a type of esophageal carcinoma (EC) that can affect any part of the esophagus, but is usually located in the upper or middle third. "Changes in the mRNA expression of EVX1 are associated with clinicopathological features in esophageal squamous cell carcinoma (ESCC)." (PMID 36814224, 2023).
nephrolithiasis (1 paper, 2023). The presence of a calculus in the pelvis of the kidney; this is most often composed of mineral salts and proteins. "Notably, rs17438465 is located between EVX1 and HIBADH, genes that have been associated with nephrolithiasis and cardiovascular disease." (PMID 37124606, 2023). "Among these, rs74637005 is located in the exonic region of NFU1, a gene previously shown to be associated with both calcium levels and elevation in metabolic biomarkers and rs17438465 is located between EVX1 and HIBADH, genes that have been associated with nephrolithiasis and cardiovascular disease." (PMID 37124606, 2023).
neuroblastoma (1 paper, 2023). Neuroblastoma (NB) is the most common solid, extracranial childhood tumor. "The directed overexpression of the human EVX1AS was able to induce the expression of EVX1 mRNA in the SHSY5Y human neuroblastoma cell line about two times (P < 0.01 for HS2)." (PMID 37670146, 2023).
pancreatic ductal adenocarcinoma (1 paper, 2022). An infiltrating adenocarcinoma that arises from the epithelial cells of the pancreas. "Several genes in the 500 kb vicinity of HOXA5 (i.e., HOXA3, HOXA9, HOXA7, HOXA1, EVX1) were also associated with high density lipoprotein (HDL) cholesterol efflux capacity, BMI, and pancreatic ductal adenocarcinoma." (PMID 35836279, 2022).
tumor (4 papers, 2013 to 2024). "EVX1 and HOXD10 are key developmental genes, playing crucial roles in cellular differentiation and tumor suppression." (PMID 39649173, 2024). "Levels of EVX1 were assessed in ESCC patients showing a significant correlation between the low levels of EVX1 expression, lymph node metastasis, and depth of tumor invasion." (PMID 31470870, 2019). "DNA hypermethylation of the ADCY5, EVX1, GFRA1, PDE9A, and TBX20 genes resulted in reduced mRNA expression in tumorous tissue samples." (PMID 23544068, 2013). "Reduced expression of the mRNAs for the ADCY5, EVX1, GFRA1 and PDE9A genes was significantly correlated with clinicopathological parameters, indicating that DNA methylation alterations, even from the precancerous stage, ultimately determine the tumor phenotype through gene silencing." (PMID 23544068, 2013).
cancer (2 papers, 2013 to 2025). A tumor composed of atypical neoplastic, often pleomorphic cells that invade other tissues. "Using CAMDAC cancer-cell-specific methylomes as input for MethSig, we observed significant enrichment of hypermethylated candidate NSCLC cancer genes known to encode differentiation and developmental transcription factors, such as PCDHGA3 and EVX1, and in ZNF-154, which may affect plasticity." (PMID 40931149, 2025).
EVX1 also shares sentences with these, for which no sentence is quoted: prostate carcinoma (2 papers); acute kidney injury (1); cardiovascular disease (1); gastric cancer (1); heart defects (1); Hypertension (1); Primary hyperaldosteronism (1); prostatic cancer (1); squamous cell carcinoma (1).